S100A13 (S100 calcium binding protein A13)
Description:
Plays a role in the export of proteins that lack a signal peptide and are secreted by an alternative pathway. Binds two calcium ions per subunit. Binds one copper ion. Binding of one copper ion does not interfere with calcium binding. Required for the copper-dependent stress-induced export of IL1A and FGF1. The calcium-free protein binds to lipid vesicles containing phosphatidylserine, but not to vesicles containing phosphatidylcholine (By similarity).
Tractability: Small molecule: a structure with a bound ligand is known; it has a binding pocket of medium quality. Antibody: its Gene Ontology location is reachable by antibodies, with high confidence; UniProt places it where antibodies can reach, with medium confidence. PROTAC: ubiquitination databases record sites on it; its protein half-life has been measured.
Gene: Protein-coding gene on chromosome 1 (153,618,612 to 153,634,442, reverse strand). Ensembl gene ENSG00000189171.
Subcellular location: Cytoplasm; Secreted
Subcellular location (Human Protein Atlas): Cytosol; Plasma membrane; Nucleoli; Nucleoplasm; Predicted to be secreted
Gene Ontology:
Molecular function: calcium ion binding; copper ion binding; fibroblast growth factor binding; protein binding; protein homodimerization activity; RAGE receptor binding; zinc ion binding; calcium-dependent protein binding
Biological process: positive regulation of canonical NF-kappaB signal transduction; positive regulation of cytokine production; positive regulation of interleukin-1 alpha production; mast cell degranulation
Cellular component: cytoplasm; cytosol; extracellular region; nucleus; perinuclear region of cytoplasm
Genetic constraint (gnomAD): Loss-of-function variants: 6 observed, 8.7 expected, observed/expected ratio (o/e) 0.69, 90% interval 0.38 to 1.36. That is too few expected variants to judge how well the gene tolerates losing a copy. Missense variants: 114 observed, 120.05 expected, observed/expected ratio (o/e) 0.95, 90% interval 0.81 to 1.11. Synonymous variants: 39 observed, 48.78 expected, observed/expected ratio (o/e) 0.8, 90% interval 0.62 to 1.04.
Homologues: Orthologues: chimpanzee S100A13 (100% identical), rat S100a13 (90% identical), rabbit S100A13 (89% identical), dog S100A13 (87% identical), guinea pig S100A13 (87% identical), mouse S100a13 (83% identical), macaque S100A13 (68% identical), zebrafish s100v1 (24% identical), zebrafish s100v2 (24% identical). Paralogues in human: S100A11 (36% identical), S100A14 (36% identical), S100A5 (36% identical), S100A1 (35% identical), S100A4 (33% identical), S100A2 (31% identical), S100A6 (31% identical), S100A12 (30% identical), S100A9 (30% identical), S100A10 (29% identical), S100A16 (29% identical), S100Z (29% identical), and 9 more.
Diseases named in the same sentence as S100A13 in open-access papers:
S100A13 is named in the same sentence as 48 diseases in open-access papers, as found by Europe PMC text mining. Sharing a sentence is not in itself a finding about the gene and the disease. The quoted sentences say what the papers report.
melanoma (20 papers, 2015 to 2025). A malignant, usually aggressive tumor composed of atypical, neoplastic melanocytes. "The overexpression of S100A13, a small S100 calcium-binding protein A13, is closely associated with high intratumoral angiogenesis and poor prognosis in lung cancer and melanoma." (PMID 33669363, 2021). "The up-regulation of S100A13 is found in thyroid cancer, malignant melanoma, and lung cancer, etc., which is associated with promoting cancer cell proliferation, invasion, and poor prognosis." (PMID 30670674, 2019). "Several studies reported positive correlation between the elevated expression of S100A13 and risk of relapse and status of melanoma patients at follow-up, indicating that S100A13 may play a crucial role in melanoma chemoresistance." (PMID 27008379, 2016). "Interestingly, S100A13 upregulation has recently been linked to resistance to the chemotherapeutic agents dacarbazine or temozolomide in melanoma patients." (PMID 25880590, 2015). "S100 subtypes: S100B, S100P, S100A4, S100A6, and S100A13 are often found in melanoma, with S100P being positive in all melanoma subtypes." (PMID 37504268, 2023). "Higher levels of S100A13 have also been found in melanoma and papillary thyroid carcinoma samples compared to normal samples." (PMID 37627239, 2023). "S100A13 was first identified as a powerfully angiogenic biomarker in some kinds of tumor such as melanoma and gliomas." (PMID 33815482, 2021). "S100A13 acts as an angiogenic marker for melanoma and has been involved in invasiveness of lung cancer cell lines." (PMID 34485305, 2021). "S100A13 is considered to be a potent angiogenic biomarker for astrocytic gliomas and melanoma, but its role in CRC is rarely reported." (PMID 33294444, 2020). "An expression analysis of S100 genes in melanoma tissues revealed that S100A13 was found highly expressed in melanoma samples, although little is known about the contribution of S100A13 to the progression of melanoma." (PMID 33256110, 2020). "In another study, S100A13 was identified as a key player in the resistance of Cutaneous Malignant Melanoma (CMM) to dacarbazine therapy, suggesting multiple roles of S100A13 in melanoma metastasis and drug resistance." (PMID 33256110, 2020). "Previously, S100A13 has been indicated to be a powerfully angiogenic biomarker for melanoma and astrocytic gliomas." (PMID 30558666, 2018). "S100A6, S100A13 and S100B have been found as overexpressed in melanoma, and likewise other S100 proteins have been identified as biomarkers in cancer of the bladder, lung and oesophagus." (PMID 25880590, 2015). "In addition, there is also a significant correlation between S100A13 expression and the survival duration of patients with melanoma." (PMID 36793711, 2023). "In addition, S100A13 is regarded as an angiogenic and prognostic biomarker in melanoma and astrocytic gliomas." (PMID 34670584, 2021). "S100A13 has been shown to promote melanoma metastasis and chemoresistance." (PMID 34485305, 2021). "While several serum biomarkers are investigated in melanoma patients, diagnostic markers currently applied in clinics are restricted to S-100, HMB-45, Melan-A, and SM5-1, and the prognostic markers to monitor melanoma progression are S100B, MART1, PMEL, and S100A13." (PMID 33302400, 2020). "S100A13 expression is upregulated in several tumor entities, such as non-small cell lung cancer (NSCLC), melanoma, and astrocytoma, and correlates with tumor angiogenesis." (PMID 39123454, 2024). "In addition S100A13 is also involved in cell cycle progression and differentiation, including cytokine and NF-κB signalling, suggesting that S100A13 may be related to increased aggressiveness of melanoma tumours." (PMID 27008379, 2016). "For example, low levels or no expression of S100A13 may be one of the key predictive markers to identify melanoma patients responding to dacarbazine\temozolomide chemotherapy." (PMID 31598164, 2019).
lung carcinoma (9 papers, 2015 to 2023). "Recently, it has been reported that S100A13 expression contributes to more aggressive invasive phenotype in lung cancer cells." (PMID 30558666, 2018). "S100A13 gene silencing in lung cancer cells has been observed to decrease the invasive potential in vitro." (PMID 25880590, 2015). "A recent study showed that S100A13 overexpression promoted migration of lung cancer cells." (PMID 33815482, 2021). "It was also reported that S100A13 increased in human astrocytic gliomas, in which it correlates with VEGF-A expression, microvessel density and tumor grading and it is also associated with a more aggressive, invasive phenotype in lung cancer-derived cell lines." (PMID 27008379, 2016). "Moreover, S100A13 was found to be involved in the invasiveness of lung cancer cell lines, and also was detected in tumor cells circulating in blood of patients with metastatic cancer, indicating that this protein may be considered as a predictor of cancer metastases." (PMID 27008379, 2016). "Furthermore, overexpression of S100A13 (P = 7.29e-4, t test), AZGP1 (P = 6.31e-4, t test), and PPT1 (P = 1.18e-4, t test), significantly increased the proliferation of lung cancer H1299 cells." (PMID 35027529, 2022).
thyroid cancer (8 papers, 2015 to 2024). "In summary, this is the first report for the association between HMGA1 and S100A13 expression in the modulation of thyroid cancer growth and invasion." (PMID 27008379, 2016). "This is the first report for the association between HMGA1 and S100A13 expression in the modulation of thyroid cancer growth and invasion." (PMID 27008379, 2016). "The effect of lentivirus-mediated S100A13 knockdown on thyroid cancer cellular oncogenic properties were evaluated by MTT, colony formation assays and transwell assays in TPC1 and SW579 cells." (PMID 27008379, 2016). "The results suggest that HMGA1 was involved in the effect of S100A13 on thyroid cancer growth and invasion by modulating the expression of Snail and E-cadherin." (PMID 27008379, 2016). "S100A13/GV248RNAi-LV-1 was transfected into thyroid cancer TPC1 cells and SW579 cells, individually." (PMID 27008379, 2016). "It was previously revealed that S100A13 had essential roles in various cancer, we therefore exploited whether S100A13 was involved in the development of thyroid cancer." (PMID 27008379, 2016). "In this study, experiments were performed to determine the effects of S100A13 on cell proliferation, and we demonstrated that the ectopic expression of S100A13 could enhance cellular proliferation of thyroid cancer TT cells in vivo." (PMID 27008379, 2016). "However, S100A13 expression in thyroid carcinoma was shown to be more common in male than that in female, and much higher in papillary cancer compared with follicular cancer and undifferentiated cancer (P = 0.049 and 0.051)." (PMID 27008379, 2016). "Moreover, the expressions of S100A13 and HMGA1 in thyroid carcinoma were shown to be associated with the patient sex and tumor types, which is not be reported in other cancers previously." (PMID 27008379, 2016). "This study establish the first link between S100A13 and HMGA1 in thyroid cancer, providing further evidence of the pivotal role of HMGA1 in thyroid cancer progression." (PMID 27008379, 2016). "In this study, we determined the effects of S100A13 on HMGA1 expression in thyroid cancer cells and examined the role of HMGA1 in thyroid cancer progression." (PMID 27008379, 2016). "The further clarification of underlying molecular events would be helpful for understanding the role of S100A13 and HMGA1 in the progression of thyroid cancer." (PMID 27008379, 2016). "Those tissue microarray data confirmed that S100A13 and HMGA1 expression were positively correlated in thyroid carcinoma, and it may be involved in the progression of thyroid cancer." (PMID 27008379, 2016). "In addition, a tissue microarray revealed that higher expressions of both S100A13 and HMGA1 were observed in thyroid cancer cases compared with that in normal thyroid cases." (PMID 27008379, 2016). "In this study, we examined the effects of S100A13 and HMGA1 on thyroid cancer progression." (PMID 27008379, 2016). "Extrapolating these findings to thyroid cancer implicates S100A13 as a new oncogenic factor in PTC, and this could warrant evaluation of the effectiveness of inhibiting S100A13-driven release of FGF-1." (PMID 25880590, 2015). "The thyroid cancer TPC1 cells, however, showed no invasive capability even in the control group, and the migration capability of TPC1 cell with the S100A13 knockdown group showed no obvious difference compared to those of the NC group." (PMID 27008379, 2016). "Furthermore, S100A13 and HMGA1 expressions were found to be positively correlated (r = 0.316, P = 0.004), when analyzed regardless of thyroid cancer types." (PMID 27008379, 2016).
glioma (7 papers, 2021 to 2025). A benign or malignant brain and spinal cord tumor that arises from glial cells (astrocytes, oligodendrocytes, ependymal cells). "Specifically, S100A8 and S100A9 were expressed in myeloid cells, S100A10 and S100A11 in various cell types, especially in glioma tumor cells, and S100A13 and S100A16 in vascular cells." (PMID 39744679, 2025). "To examine the molecules that interact with S100A13 in the presence of Ca2+, we attempted to perform pull-down experiments using StrepTactinTM MicroPrep® resin beads and cytosol fraction from C6 glioma cells expressing Strep-tagII-S100A13." (PMID 37371039, 2023). "In our previous study, we developed an S100 family-based prognostic signature consisting of five genes of S100A11, S100A16, S100B, S100PBP and S100A13 for glioma patients." (PMID 37151881, 2023). "When C6 glioma cells were treated with serum deprivation stress, the cell contents of ProTα and S100A13 decreased, while p65 and p40 Syt-1 levels were completely lost." (PMID 37371039, 2023). "The specificity was observed in the finding that large amounts of S100A13 and Syt-1 were lost due to serum deprivation in C6 glioma cells pretreated with heat-inactivated BoNT1." (PMID 37371039, 2023). "Amlexanox (Amx) inhibited the association between S100A13 and ANXA2 in C6 glioma cells cultured under serum-free conditions in the in situ proximity ligation assay." (PMID 33807671, 2021). "S100A13 was demonstrated as a dimer partner in a previous study using the same C6 glioma lysates both in the absence and presence of Ca2+, which were used also in the present study." (PMID 33807671, 2021). "In contrast, both Syt-1 and S100A13 remained in the C6 glioma cells cultured under serum-free conditions following anti-ANXA2 antibody delivery." (PMID 33807671, 2021). "In this experiment both intracellular signals of synaptotagmin-1 (Syt-1) and S100A13 were reduced in C6 glioma cells cultured under serum-free conditions following normal goat antibody delivery." (PMID 33807671, 2021). "The tight interaction between both proteins was supported by the in situ PLA assay, in which intense amplified signals were observed 1.5 and 3 h after the serum deprivation of C6 glioma cells in the presence of amlexanox, which prevents the extracellular release of S100A13." (PMID 37371039, 2023). "To evaluate the association of S100A13 and ANXA2 induced by serum-free conditions in C6 glioma cells, we adopted the in situ PLA technique, which could amplify the fluorescent signal owing to the interaction between S100A13 and ANXA2." (PMID 33807671, 2021). "Prothymosin alpha (ProTα) and S100A13 are released from C6 glioma cells under serum-free conditions via membrane tethering mediated by Ca2+-dependent interactions between S100A13 and p40 synaptotagmin-1 (Syt-1), which is further associated with plasma membrane syntaxin-1 (Stx-1)." (PMID 33807671, 2021). "According to this idea, gliomas could be classified according to a hypoxic inflammation linked with S100A9 expression, a perivascular inflammation related to S100A11 expression, and a microglial inflammation associated to S100A13 expression." (PMID 39744679, 2025). "Conversely, S100A13 could be linked to the physiological function of microglia located in the periphery of gliomas and may play a more relevant role in the glioma invasion processes, irrespective of their aggressiveness." (PMID 39744679, 2025). "To examine whether ANXA2 associates with S100A13, the cargo protein mediating stress-induced non-classical release under serum-free conditions, we first performed a pull-down assay using the lysates of C6 glioma cells expressing Strep-tagII-S100A13 in the absence or presence of 100 μM of Ca2+." (PMID 33807671, 2021). "However, this relationship was only relevant for S100A11 expression in IDH mut gliomas and no conclusive evidence was obtained regarding the prognostic role of S100A13 in tumor progression." (PMID 39744679, 2025).
glioma (continued). "Immunoblot analysis result showing that S100A13, but not ANXA2, is lost in C6 glioma cells under serum-free conditions is noteworthy." (PMID 33807671, 2021).
ovarian carcinoma (6 papers, 2005 to 2025). A malignant neoplasm originating from the surface ovarian epithelium. "We found that the expression of BANF1, CDK2AP2, DDT, LRIG1, MRPL4, and S100A13 was upregulated in ovarian cancer samples, and the expression of EPS8, NUCB2, PAF1, PMP22, RABGAP1L, and USO1 was upregulated in normal samples." (PMID 41000388, 2025). "While, the S100A12 (HR = 0.56, 95%CI: 0.41–0.78, P = 0.0043), S100A13 (HR = 0.73, 95%CI: 0.53–1.01, P = 0.058) and S100Z (HR = 0.6, 95%CI: 0.37–0.96, P = 0.032) expression predicted better prognosis in grade II ovarian cancer patients." (PMID 30558666, 2018). "Co-expression of previously identified markers for ovarian cancer including kallikreins 6 and 10 as well as the S100 calcium-binding proteins S100A1 and S100A13 was also seen." (PMID 16042759, 2005).
breast carcinoma (4 papers, 2017 to 2024). "The findings suggest that S100A13 is involved in zinc homeostasis of breast cancer cells." (PMID 38249992, 2024). "Moreover, the upregulation of metal binding protein S100A13 likely plays a role in zinc homeostasis of breast cancer cells." (PMID 38249992, 2024).
pulmonary fibrosis (4 papers, 2021 to 2025). Chronic progressive interstitial lung disorder characterized by the replacement of the lung tissue by connective tissue, leading to progressive dyspnea, respiratory failure, or right heart failure. "The importance of their normal function is evident from the observation that simultaneous mutations in S100A3 and S100A13 predispose individuals to early-onset pulmonary fibrosis, underscoring their critical role in lung health." (PMID 41164170, 2025). "S100A3 and S100A13 mutations are particularly relevant in the context of familial early-onset pulmonary fibrosis (PF), with our research showing that these mutations disrupt key cellular processes that contribute to fibrosis." (PMID 41164170, 2025). "Patients with digenic S100A3 and S100A13 mutations exhibited an atypical and progressive interstitial pulmonary fibrosis, with impaired intracellular calcium homeostasis and mitochondrial dysfunction." (PMID 38099297, 2023). "Recently, two variants in the calcium-binding protein genes S100A3 (NM_002960) and S100A13 (NM_001024210) were identified, segregating with the disease in seven siblings from two unrelated families with pulmonary fibrosis." (PMID 40497957, 2025). "S100A13 is a calcium binding protein gene, the digenic mutations of S100A13 would break calcium homeostasis, distort ECM and result in progression of lung fibrosis." (PMID 34670584, 2021). "This iPSC disease model is the first to replicate the role of S100A3 and S100A13 in lung fibrosis." (PMID 40497957, 2025).
atherosclerosis (3 papers, 2015 to 2024). A disease characterized by the build-up of fatty material and calcium deposition in the arterial wall resulting in partial or complete occlusion of the arterial lumen. "We next examined whether oxidative stress by H2O2 stimulated S100A13 release from CASMCs, because oxidative stress has been implicated in the pathogenesis of vascular abnormalities such as atherosclerosis and hypertension." (PMID 26418160, 2015). "S100A13 is distributed on the surface of atherosclerosis, and podoplanin is detected in the interior of advanced atherosclerosis, and the different localization of S100A13 and podoplanin may be related to the different effects." (PMID 34177942, 2021).
gastric cancer (3 papers, 2008 to 2022). A primary or metastatic malignant neoplasm involving the stomach. "For instance, increased expression of S100A13 was strongly associated with worse survival in gastric cancer (GC) patients." (PMID 35300639, 2022). "S100A13, not detectable in SAGE libraries, was shown to be highly expressed in gastric cancer tissues by EST virtual Northern blot." (PMID 18793447, 2008).